SOX6 (SRY-box transcription factor 6)
Diseases named in the same sentence as SOX6 in open-access papers (continued):
Sharing a sentence is not in itself a finding about the gene and the disease.
cervical cancer (continued). "Further, the sensitivity of cervical cancer cells to cisplatin chemotherapy could be reduced by the SOX6-induced autophagy in vitro and in vivo, while such a phenomenon could be turned over by autophagy-specific inhibitor and MAP4K4 inhibitor, respectively." (PMID 34930918, 2021). "Taken together, these results suggested that the sensitivity of cervical cancer cells to cisplatin could be increased by inhibiting SOX6-induced autophagy through both autophagy and MAP4K4 inhibitors." (PMID 34930918, 2021). "However, the final cell fate and significance of these cell‐cycle‐arrested cervical cancer cells induced by SOX6 remains unclear." (PMID 38383842, 2024). "In addition, the SOX6‐induced senescent cervical cancer cells are resistant to cisplatin treatment." (PMID 38383842, 2024). "This study uncovers the mechanism of SOX6-induced autophagy and its clinical significance in the sensitivity of cervical cancer cells to cisplatin chemotherapy, which may provide possible explanations for the poor response of cervical cancer patients to platinum-based chemotherapy." (PMID 40396003, 2022). "Furthermore, SOX6 could significantly inhibit the cisplatin-induced apoptosis of cervical cancer cells dependent on its HMG domain in vitro and in vivo." (PMID 34930918, 2021). "Therefore, to further investigate whether the SOX6-induced autophagy affected the therapeutic effect of cisplatin in cervical cancer cells, the effect of SOX6 in the cisplatin-induced apoptosis was firstly analyzed by flow cytometry analysis." (PMID 34930918, 2021). "This study uncovered the mechanism of SOX6-induced autophagy in cervical cancer cells and its role in regulation of the sensitivity to cisplatin chemotherapy, which might explain the underlying reason for the poor response of partial cervical cancer patients to the platinum-based chemotherapy." (PMID 34930918, 2021). "Moreover, the sensitivity of cervical cancer cells to cisplatin could be increased by inhibiting SOX6-induced autophagy through both autophagy and MAP4K4 inhibitors." (PMID 34930918, 2021). "Based on the phenomenon that the SOX6-induced autophagy mediated by MAP4K4 could reduce the sensitivity of cervical cancer cells to cisplatin treatment, we further investigated whether the sensitivity to cisplatin could be increased by inhibiting autophagy or MAP4K4 expression." (PMID 34930918, 2021). "SRY‐box transcription factor 6 (SOX6) is a member of the SOX gene family and inhibits the proliferation of cervical cancer cells by inducing cell cycle arrest." (PMID 38383842, 2024). "The results revealed that the levels of SOX6 protein and its downstream MAP4K4 protein in the frozen cervical cancer tissues of patients who were sensitive to cisplatin were lower than those in patients who were not sensitive to cisplatin." (PMID 34930918, 2021). "In this study, we firstly found that SOX6-induced autophagy of cervical cancer cells depending on its HMG domain, and MAP4K4 gene was identified as the potential target gene of SOX6 through microarray and RNA-sequencing analyses." (PMID 34930918, 2021). "In turn, we found that both the level of endogenous SOX6 protein and its induced autophagy are significantly increased under cisplatin treatment, and accompanied by an increased level of MAP4K4, activation of the MAPK/ERK pathway, and inhibition of the PI3K-AKT-MTOR pathway in cervical cancer cells." (PMID 40396003, 2022). "In this study, we further found that MAP4K4 could mediate the SOX6-induced autophagy through inhibiting PI3K-Akt-mTOR pathway and activating MAPK/ERK pathway, which could reduce the sensitivity of cervical cancer cells to cisplatin chemotherapy in vitro and in vivo." (PMID 34930918, 2021).
cervical cancer (continued). "Moreover, cisplatin itself could promote the expression of endogenous SOX6 and subsequently the MAP4K4-mediated autophagy in cervical cancer cells, which might in turn reduce the sensitivity of these cells to cisplatin treatment." (PMID 34930918, 2021).
breast carcinoma (12 papers, 2012 to 2025). "SOX6 downregulation was also found in prostate cancer, hepatocellular carcinoma, lung cancer, and breast cancer, while its downregulation was associated with the malignant phenotype of neoplasms." (PMID 34868396, 2021). "The findings revealed a higher expression of SOX6 protein in normal breast epithelial cells contrast with breast cancer cell lines." (PMID 39619607, 2024). "Previous studies have shown that SOX6 is downregulated and serves as a tumor growth inhibitor in many cancers, including breast cancer, lung adenocarcinoma, osteosarcoma, prostate cancer, and esophageal cancer." (PMID 39619607, 2024). "Employing the breast cancer tissue microarray from Shanghai Outdo Biotech, a correlation analysis was conducted on the immunohistochemical expression of SOX6 in relation to clinical prognosis." (PMID 39619607, 2024). "The analyses of The Cancer Genome Atlas, Cancer Cell Line Encyclopedia and Genotype-Tissue Expression datasets, indicate that SOX6 expression is decreased in breast cancer samples." (PMID 38132438, 2023). "It is worth remarking that SOX6 and HEY1 are transcription factors associated with esophageal squamous cell carcinoma and breast cancer respectively, even though their roles in breast cancer and chemotherapy have not been thoroughly defined." (PMID 29540829, 2018). "In addition, we also detected the effects of 15 TFs on the proliferation function of breast cancer cells, among which knockdown of SOX6, SOX15, or CEBPG significantly inhibited the proliferation of Hs578T and BT549 cells, respectively." (PMID 40397381, 2025). "Ultimately, we hypothesized and confirmed that miR-499-5p might mediate the suppressive effects of propranolol on EMT and metastasis in breast cancer 4T1 cells by targeting Sox6." (PMID 38294713, 2024). "SOX6, belonging to the SOX family, has shown its anti-tumor properties in various tumors including breast cancer." (PMID 39619607, 2024). "Next, SOX6 protein levels were detected in a normal human breast epithelial cell line (MCF-10A) and several human breast cancer cell lines (T47D, BT-549, MCF-7, MDA-MB-231)." (PMID 39619607, 2024). "Furthermore, it has been demonstrated that Sox6 is a target gene of miRNA-499-5p, and recent studies have suggested that Sox6 may function as an EMT inhibitory factor in tumors, including breast cancer." (PMID 38294713, 2024).
hepatocellular carcinoma (10 papers, 2016 to 2024). A malignant tumor that arises from hepatocytes. "The expression level of SOX6 in hepatocellular carcinoma is negatively associated with tumor stage, and patients with down‐regulated expression of SOX6 show poor prognosis." (PMID 31729835, 2020). "In hepatocellular carcinomas, the relationship between SOX6 and LIN28B expression is less clear indicating more intricate regulatory dynamics." (PMID 38704454, 2024). "Sox6 is down‐regulated in hepatocellular carcinoma in correlation with poor prognosis." (PMID 29369542, 2018). "It was reported that miR-96 targeted the 3ʹ-UTR of SOX6, FOXO1 and FOXO3a in hepatoma cells." (PMID 33046975, 2020).
Obesity (10 papers, 2008 to 2024). Accumulation of substantial excess body fat. "Our study identified in the male subjects SOX6 as a potential pleiotropic gene underlying both obesity and osteoporosis." (PMID 19714249, 2009). "Information on the SOX6 gene SNPs bivariately associated with obesity and osteoporosis phenotypes in the male subjects of our GWAS." (PMID 19714249, 2009). "In summary, using a novel bivariate GWAS approach, we identified a gene, SOX6, which appeared to be important to co-variation of both obesity and osteoporosis risk phenotypes in male subjects." (PMID 19714249, 2009). "Through bivariate association analyses, we identified the SOX6 gene (SRY-box 6) as a potential pleiotropic gene underlying both obesity and osteoporosis." (PMID 19714249, 2009). "Another cross-sectional study revealed that the minor alleles A/C of rs7117858 SNP, located downstream of SRY-box transcription factor 6 or SOX6, was associated with lower bone mass, as measured by quantitative ultrasonography and obesity in Caucasian young adults." (PMID 35883424, 2022). "Genome-wide association studies suggest that Sox6 influences both obesity and osteoporosis." (PMID 24662752, 2014). "Our findings, together with the prior biological evidence, suggest the SOX6 gene's importance in co-regulation of obesity and osteoporosis." (PMID 19714249, 2009). "Although some evidence suggests the potential role of the SOX6 gene in co-variation of obesity and osteoporosis phenotypes, the finding still needs to be replicated in studies of a larger-scale." (PMID 19714249, 2009). "In respect to the gene's relevance to obesity, two recent studies identified that SOX6 plays an important role in obesity-related insulin resistance." (PMID 19714249, 2009). "Furthermore, it has been reported that rs543874 decreases the binding of SOX6, which was considered a transcription factor contributing to the developmental origins of obesity by promoting adipogenesis." (PMID 35295960, 2022). "Similarly, SOX6 contributes to the developmental origin of obesity by promoting adipogenesis, and has a key role in adipocyte differentiation." (PMID 29914366, 2018). "Of note is that the SOX6 gene and its SNPs would not have been discovered for the significance to obesity and osteoporosis in our GWAS if only univariate association analyses were performed." (PMID 19714249, 2009). "Interestingly, SOX6 was previously found to be essential to both cartilage formation/chondrogenesis and obesity-related insulin resistance, suggesting the gene's dual role in both bone and fat." (PMID 19714249, 2009).
colorectal cancer (9 papers, 2017 to 2023). A primary or metastatic malignant neoplasm that affects the colon or rectum. "MiR-766 was found to promote cell proliferation by targeting SOX6 in colorectal cancer, and its increased expression was associated with worse overall survival in patients with lung adenocarcinoma." (PMID 30052636, 2018). "MiR-766 has been shown to be upregulated in colorectal cancer and to be associated with promotion of cell proliferation and anchorage-independent growth by targeting SOX6 in the colorectal adenocarcinoma line SW480." (PMID 28430625, 2017). "In contrast, miR-766 has been reported to promote cell proliferation of human colorectal cancer by regulating SOX6 expression." (PMID 28537886, 2017). "Moreover, both CUL2 and SOX6 are associated with colitis as well, while SERPINB9 and NINJ2 have been associated with colorectal cancer." (PMID 35371111, 2022). "MiR-766 targets SOX6 to promote cell proliferation in colorectal cancer." (PMID 35083181, 2022).
melanoma (7 papers, 2020 to 2026). A malignant, usually aggressive tumor composed of atypical, neoplastic melanocytes. "Collectively, these results demonstrate that C1/C2 melanoma cells with elevated SOX6 expression drive tumor invasiveness." (PMID 40866912, 2025). "Our results reveal that SOX6-high C1/C2 melanoma subpopulations exhibit immune cell exclusion, metabolic dysregulation and enhanced invasive capacity, similiar to advanced metastasis." (PMID 40866912, 2025). "This study suggests that SOX6-overexpressing melanoma cells are the main driver subpopulation promoting early invasion of AM and establishes SOX6 and fatty acid transport processes as biomarkers and potential therapeutic targets for early melanoma metastasis." (PMID 40866912, 2025). "Our results indicate that SRY-Box Transcription Factor 6 (SOX6)-positive melanoma cells in early AM metastasis are strongly invasive." (PMID 40866912, 2025). "Our results indicate the key coordinator role of SOX6 in promoting the invasive capacity of melanoma cells and driving metastasis." (PMID 40866912, 2025). "The transcription factor SOX6 is overexpressed in microsatellite lesions and marks a population of highly invasive melanoma cells." (PMID 40866912, 2025). "Our findings enhance the understanding of the mechanisms driving melanoma progression and highlight the potential for SOX6 as a therapeutic target for managing early AM invasiveness." (PMID 40866912, 2025). "These complementary in vitro experiments collectively establish SOX6 as a critical regulator of melanoma cell proliferation, migration, and invasion." (PMID 40866912, 2025). "The SOX6_OE-driven metastatic lesions exhibited enhanced tumor heterogeneity, highlighting SOX6 function in driving melanoma cell differentiation." (PMID 40866912, 2025). "Transcripts related to melanoma progression and poor prognosis (Sox6, Sox11, Tfap2a, Myo7a) were upregulated in IgG-treated animals." (PMID 38740748, 2024). "Dlx4os knockdown redirected melanoma cells to a more differentiated and less malignant phenotype, confirmed by differential expression of phenotypic state markers (Sox10, Mitf, Tgfβ, Sox6, Mlana), reduced their invasive and migratory potential, and delayed tumour progression in vivo." (PMID 41855479, 2026). "The up-regulation of CPT1, ACSL3, SLC27A5, and associated PC content was primarily detected in SOX6 + C1/C2 melanoma cells, suggesting that fatty acid transport, rather than fatty acid oxidation, constitutes the primary mechanism in AM metastasis." (PMID 40866912, 2025). "Therefore, our results are consistent with a mechanism for SOX6 in promoting melanoma via regulation of fatty acid metabolism." (PMID 40866912, 2025). "Our results reveal an invasive C1/C2 melanoma cells subpopulations marked by high SOX6 expression." (PMID 40866912, 2025). "Notably, the C1 and C2 cell subpopulations - characterized by high SOX6 expression - were functionally validated through SOX6 overexpression (SOX6_OE) and knockout (SOX6_KO) models to promote glycolytic dysregulation in melanoma cells." (PMID 40866912, 2025). "Collectively, our results indicate that SOX6 overexpression promotes the glycolytic process and increases the content of long-chain phospholipids such as PE/PC by disrupting fatty acid transport and fatty acid metabolism to promote tumor invasion in C1/C2 melanoma cells." (PMID 40866912, 2025). "Conversely, SOX6 knockout (SOX6_KO) in A375 and SOX6 knockdown (SOX6_KD) SK-MEL-28 melanoma lines demonstrated reciprocal phenotypes: markedly impaired invasiveness, diminished migration, and reduced proliferation." (PMID 40866912, 2025). "A second region targeting rs7108091 (interacts with SOX6, MPRA-significant in melanocytes and melanoma) showed marginal reductions for two gRNAs." (PMID 39802764, 2024).
melanoma (continued). "Only one of the five regions (targeting both rs1455114 and rs1455115; interact with SOX6; located within melanocyte enhancer; within ATAC-open region in melanocytes and melanoma) showed a reduction of SOX6 by a single guide (0.71 fold expression relative to NTC1)." (PMID 39802764, 2024).
osteoarthritis (7 papers, 2014 to 2023). A noninflammatory degenerative joint disease occurring chiefly in older persons, characterized by degeneration of the articular cartilage, hypertrophy of bone at the margins and changes in the synovial membrane. "These include genes associated with cartilage formation (SOX6), inflammation and osteoarthritis (SAA) and muscle cell differentiation and muscle regeneration (MYOD1, SERGEF)." (PMID 25270232, 2014). "The dysregulation in the function of SoxD proteins (i.e. Sox5, Sox6, Sox13, and Sox23) have been implicated in different disease conditions such as chondrodysplasia, cancer, diabetes, hypertension, autoimmune diseases, osteoarthritis among others." (PMID 33230925, 2020). "Aggrecan, Col-10, MMP-13, SOX6, and Runx2 are closely related to osteoarthritis." (PMID 34926690, 2021). "Sox6 and Sox9 are also important factors in cartilage homeostasis that stimulate cartilage formation, which may promote bone growth and prevent osteoarthritis." (PMID 32946669, 2020). "HBM has been associated with both ligament ossification and increased prevalence of joint replacement (potentially due to osteoarthritis) and, more recently, genetic markers for MEF2C and SOX6, which both have regulatory roles in endochondral ossification." (PMID 24606091, 2014). "COL2A1 and ACAN genes are directly associated with the Osteoarthritis pathway, which are represented by the solid lines, while COL1 and SOX6 are not, which are represented by the dotted lines." (PMID 34970658, 2019).
osteoporosis (7 papers, 2009 to 2024). A condition of reduced bone mass, with decreased cortical thickness and a decrease in the number and size of the trabeculae of cancellous bone (but normal chemical composition), resulting in increased fracture incidence. "Sex determining region Y-box 6 (SOX6), an osteoporosis susceptibility gene shown by genome-wide association studies, was up-regulated by more than twofold by 1α,25(OH)2D3 in hP29SN." (PMID 24116037, 2013). "In addition, the association between SOX6 and osteoporosis has been documented." (PMID 32496000, 2020). "Meanwhile, SOX6 is a multi-effector gene in osteoporosis, and there is a latent interaction between its multiple genetic mutations and the risk of osteoporosis." (PMID 38205152, 2024). "A large‐scale meta‐analysis identified Sox6 as a candidate gene that increased bone mineral density and thereby improved osteoporosis in women." (PMID 32946669, 2020). "In our study, we found that miR‐17‐3p suppressed osteoblast differentiation by downregulating the expression of Sox6, although the clinical significance of this observation in the context of OS or osteoporosis remains to be determined." (PMID 32946669, 2020). "It was reported that SOX6 is necessary for effective cartilage formation, as its inactivation can affect the differentiation of chondrocytes and neuronal cells, resulting in mild bone defects and bone-related disorders like Tolchin-Le Caignec syndrome, osteoporosis, and osteochondroma." (PMID 38205152, 2024). "Our findings suggested that SOX6, ACE, SYK and TGFB3 may play important roles in the bone formation of osteoporosis in postmenopausal women." (PMID 32496000, 2020).
cardiac hypertrophy (6 papers, 2016 to 2025). "Moreover, the inactivation of miR-208a hampered the induction of the βMyHC gene in mice with cardiac hypertrophy and was associated with increased SOX6 in those with cardiac hyperaldosteronism." (PMID 36140281, 2022). "Among these, Egr1 in cluster J4, which is involved in angiogenesis, cardiac hypertrophy, and cardioprotection, demonstrated significantly decreased expression at P7 and P14 in the Sox6 KO hearts compared to control." (PMID 27832192, 2016). "Additionally, scGO identified genes such as ZBTB20, ESRRG, and SOX6, which have established links to the onset of cardiac hypertrophy." (PMID 39820437, 2024). "Myocardial elevation of miR-499 without significant alteration of SOX6 has been quantitatively associated with the up-regulation of the βMyHC gene, cardiac hypertrophy, and an increase in cardiomyocyte size, but also with genes associated with stress-induced cardiac dysfunction in mice." (PMID 36140281, 2022).